IL6 (interleukin 6)
Diseases named in the same sentence as IL6 in open-access papers (continued):
Sharing a sentence is not in itself a finding about the gene and the disease.
liver fibrosis (continued). "A study illustrated that dual inhibitors of sEH and COX-2 improved hepatic fibrosis and portal hypertension and downregulated IL-6 levels, suggesting that IL-6 plays a driving role in hepatitis." (PMID 36364213, 2022). "Consistently, hepatic expression levels of genes, including a progenitor cell marker (Sox9), a liver fibrosis marker (Acta2), and an inflammation marker (Il6), were decreased in Sesn1−/−-BDL vs." (PMID 34880414, 2022). "Previous research found that macrophages secreted IL-1β and IL-6, which promoted hepatocyte injury and liver fibrosis." (PMID 35603224, 2022). "SESN1 mediates the effect of miR-200c on the proliferative and neuroendocrine-like capacity (of producing the mitogenic IL-6) of cholangiocytes and engages in the pathogenesis of liver fibrosis." (PMID 34880414, 2022). "In order to verify that the effect of CGEA on liver fibrosis in experimental rats is achieved by reducing liver inflammation, we determined the levels of IL-6 and TNF-α in rat liver tissue using the ELISA method." (PMID 33995112, 2021). "And our results table that CGEA significantly reduced serum levels of IL-6 both in acutely inflamed mice and in rats with liver fibrosis." (PMID 33995112, 2021). "The association between markers of inflammation and non-invasive measures of liver fibrosis has been previously studied, and markers of inflammation (e.g., IL-6) can predict the presence of advanced liver fibrosis (ALF) in HIV-infected patients." (PMID 34441792, 2021). "Induction of liver fibrosis in rats using TAA for 6 weeks resulted in a significant elevation in hepatic contents of IL-6 and TNF-α, as compared to the normal group." (PMID 33628797, 2021). "TNF-α and IL-6 are proinflammatory factors with the synergistic effect, which can promote the progress of liver fibrosis and inflammation in patients, while the incidence of adverse reactions in patients is the key index to evaluate the effect of drug therapy." (PMID 34484339, 2021). "Upon TLR activation, cells produce proinflammatory cytokines such as TNF-α, IL-6, IL-1, and monocyte chemoattractant protein-1, which further contribute to liver fibrosis." (PMID 34422075, 2021). "Liver fibrosis in LD-mouse models is often limited and requires a “second-hit” such as carbon tetrachloride or inflammatory insult (e.g., IL6) in order to produce detectable hepatic fibrosis." (PMID 33770118, 2021). "Systemic inflammation is another key indicator of the pathogenesis of liver fibrosis, and IL-6, TNF-α, and TGF-β are the main cytokines in this pathological condition." (PMID 34549998, 2021). "One study reported reduced liver fibrosis and hepatic gene expression of Interleukin-6 (IL-6) in BDL rats when using the probiotic Lactobacillus rhamnosus GG45." (PMID 33500487, 2021). "In hepatic fibrosis, pro-inflammatory cytokines, including IL-1, IL-6, and TNF-α, generated by Kupffer, hepatocytes, and infiltrating inflammatory cells promote liver damage." (PMID 34764877, 2021). "During liver fibrosis, HSCs are a cellular source of IL-6, and IL6 transcription is enhanced via the hepatic leukaemia factor (HLF) transcription factor." (PMID 34047814, 2021). "Our findings confirmed that IL-6 production, macrophage infiltration, and the number of bile ducts increased in liver fibrosis." (PMID 35004731, 2021). "Changes in hepatic fibrosis-related cytokines (interleukin (IL)-1b and IL-6) and in hepatic collagen mRNA expression were observed when comparing adult male offspring exposed to gutkha in utero to those not exposed." (PMID 33126512, 2020). "CCL2 and IL-8 act as chemoattractants, IL-6 is the major cytokine in acute phase response and osteopontin is a central mediator of liver fibrosis." (PMID 33003572, 2020). "IL-6 has already been identified as a factor with biological effects in patients with liver fibrosis and HCC." (PMID 33028209, 2020). "The results demonstrated that RTA and RTB inhibited the production of NO, TNF-α, and IL-6 and suppressed liver fibrosis." (PMID 33224259, 2020).
liver fibrosis (continued). "The effect of cranberry nutraceutical (50 and 100 mg/kg) on oxidative stress markers, antioxidant enzymes, NF- κB levels in livers tissues, and serum levels of TNF-α and IL-6 in HFCD-induced liver fibrosis in rats." (PMID 32256346, 2020). "We found that the severity of liver fibrosis and the serum level of IL-6 both increased over time upon CCl4 injection, while the relative expression of hsa_circ_0004018 was downregulated." (PMID 32584784, 2020). "Based on results of network pharmacology, it was known that flavonoids can possibly suppress liver fibrosis by inhibiting the IL-17 signaling pathway, which includes NF-κB, AP-1, IL-6, IL-1β, TNFα, IFN-γ, CCL2, COX2, MMP1, MMP3, and MMP9." (PMID 33551818, 2020). "Compared to the untreated liver fibrosis group, the expression of inflammatory factors including IL-1, IL-2, IL-6, IL-8, IL-10, and TNF-α were significantly decreased in the hBM-MSCs and hBM-MSCs-Ex treatment groups (p < 0.05)." (PMID 30885249, 2019). "Our observations that CCl4 injection induced elevation of IFN-γ, TNF-α, and IL-6 and aggravation of liver fibrosis in this study are consistent with these previous conclusions." (PMID 30635047, 2019). "During cholestasis, excessive inflammatory responses can activate the TLR4 signaling pathway, which promotes NF-κB activation to secrete more proinflammatory cytokines, like TNF-α and IL-6, to aggravate inflammatory damage and liver fibrosis." (PMID 31827690, 2019). "The activation of hepatic stellate cells by IL6/STAT3 to promote liver fibrosis has been documented in F. hepatica infection in humans and mice which is in line with our findings in terms of the activation status of the IL6 and STAT3 signaling pathways at W14." (PMID 31555289, 2019). "Studies have also demonstrated that TNF-α and IL-6 play important roles in the development of liver fibrosis." (PMID 30635047, 2019). "Injection of etanercept-secretome also resulted in the significantly lower serum levels of liver enzymes as well as pro-inflammatory cytokines, such as TNF-α and IL-6, in the mice with liver fibrosis." (PMID 31847135, 2019). "Both TNF-α and IL-6 are involved in the conversion of HSCs into myofibroblasts that contribute to liver fibrosis." (PMID 30096951, 2018). "This is consistent with reports that associate the lack of IL-6 with increase in liver injury and the recent potential therapeutic ability of IL-6 to reverse liver fibrosis." (PMID 30546364, 2018). "The current study represents the first report that highlights the inhibitory effect of BM-MSCs on IL6/STAT3 pathway in liver fibrosis." (PMID 30346985, 2018). "Leptin can promote an inflammatory response by activating the secretion of proinflammatory cytokines, such as TNF-α, IL-6, and IL-12 in liver fibrosis." (PMID 29436483, 2018). "Significant increase in NF-κB p50, NF-κB p65, TNF-α and IL-6 mRNA expressions were detected in CCl4-induced liver fibrosis in mice, compared to control." (PMID 30150935, 2018). "We further demonstrate for the first time the possible protective role of IL-6 against severe hepatic fibrosis in a population chronically exposed to S. mansoni parasites." (PMID 29610679, 2018). "A recent study demonstrated that IL-6 and murine MSCs synergistically enhanced hepatic repair, improved hepatic function, and reduced liver fibrosis in mice." (PMID 28583205, 2017). "Nevertheless, a balance of IL-6 is very important since transcriptionally enhanced IL-6 strongly facilitates the activation of human hepatic stellate cells favoring the advance of liver fibrosis." (PMID 29214184, 2017). "We have recently demonstrated that depletion of adenosine deaminase acting on double-stranded RNA (ADAR1) from mouse hepatocytes leads to HSC activation and induction of inflammation and hepatic fibrosis that is mediated by interleukin 6 (IL-6)." (PMID 28472150, 2017).
liver fibrosis (continued). "Since HSCs play a crucial role in the development of liver fibrosis, we investigated the possibility of a direct effect of IL-6 on their activation and explored the signal transduction pathways involved in this process." (PMID 28472150, 2017). "IL-6 is the predominant regulator of the hepatic acute-phase response and modulates liver fibrosis through degrading extracellular matrix proteins by inhibition of proteases or by binding to other cytokines." (PMID 26949702, 2016). "Genes encoding IL6, CRP and NOS2 were previously reported to exhibit dysregulation in liver fibrosis." (PMID 27135246, 2016). "Interleukin-6 increased significantly in bleomycin-induced pulmonary fibrosis and other fibrosis diseases such as liver fibrosis, cystic fibrosis, and systemic scleroderma." (PMID 28194150, 2016). "In this study, we found that BBG significantly ameliorated liver fibrosis and down-regulated fibrosis-related pro-inflammatory cytokines IL-6, TNF-α, IL-1β, and PDGF." (PMID 25933224, 2015). "Consistent with the results, we observed that the liver fibrosis was significantly reduced and the inflammation response was obviously alleviated by the down-regulation of pro-inflammatory cytokines IL-6 and TNF-α after the treatment with PZQ." (PMID 25582427, 2015). "Kupffer cells and T lymphocytes and the fibrotic and inflammatory cytokines, such as TGF-β, TNFα, IL-6, and IL-17, produced by them are also involved in the progression of hepatic fibrosis and activation of hepatic stellate cells." (PMID 26358689, 2015). "Other transcription factors like nuclear factor-like 2 (Nrf2) and cytokines (TNF-α, IL-6, IL-13) can also activate HSCs and promote liver fibrosis." (PMID 25897319, 2015). "In this work we observed a strong anti-inflammatory effect of Omegaven® on human monocytes activated by LPS, nearly suppressing IL-6, IL-8, IL-1β and TNFα whose elevated levels have been associated previously with NASH and liver fibrosis." (PMID 25502575, 2014). "Earlier studies revealed that B-cells evidently contribute to the development of liver fibrosis by the production of profibrotic cytokine IL-6 that induces the differentiation of hepatic stellate cells into myofibroblasts and raise collagen synthesis." (PMID 24579055, 2014). "Analysis of MSC and IL-6 treatment on liver fibrosis was measured by histopathology, PAS, TUNEL and Sirius red staining, RT-PCR, and liver function tests for Bilirubin and Alkaline Phosphatase (ALP)." (PMID 23531302, 2013). "Recent evidence shows that IL-6 can enhance hepatocyte survival while IL-6 depleted mice have enhanced liver fibrosis." (PMID 23531302, 2013). "In LPS challenge and liver fibrosis models, the proinflammatory cytokines MCP-1, KC, and RANTES were normally induced and able to compensate for loss of TNF-α and IL-6 and elicit a normal inflammatory response." (PMID 22996371, 2013). "Hepatocytes in fatty liver or fat infiltration will induce inflammation by cytokine secretion of IL-6 and further process into liver fibrosis lesions." (PMID 23843869, 2013). "We demonstrate that IL-6 and MSCs synergistically enhance hepatic repair, reduce liver fibrosis and improve overall hepatic function compared to either of the treatments alone." (PMID 23531302, 2013). "Since elevated TNF-α and IL-6 are also acknowledged to play crucial roles on hepatic fibrosis, these findings did provide a rational connection between B19 NS1 and liver fibrosis in SLE." (PMID 23840852, 2013). "Nine muscle pathways were identified, including inflammatory (hepatic fibrosis and IL-6), lipid metabolic (PPARα, PPARγ and sphingolipids) and carbohydrate metabolic (pyruvate and propanoate) pathways." (PMID 23251491, 2012). "This discrepancy may reflect differences in disease etiology and immune responses, highlighting the complexity of Il-6 signaling in liver fibrosis." (PMID 41474968, 2026). "Therefore, Tet2−/− pMDMs secrete elevated IL-6, which promotes HSCs activation and contributes to liver fibrosis." (PMID 41474968, 2026).
liver fibrosis (continued). "GDF‐15 correlated with hepatic dysfunction (MELD Spearman's ρ: 0.50; albumin ρ: −0.57), HVPG (ρ: 0.47), systemic inflammation (C‐reactive protein ρ: 0.45; interleukin 6 [IL‐6] ρ: 0.55; procalcitonin ρ: 0.58), liver stiffness (ρ: 0.67) and enhanced liver fibrosis test (ρ: 0.64) (all p < 0.001)." (PMID 41555670, 2026). "Additionally, FXR modulates inflammation by suppressing pro-inflammatory cytokines (TNF-α, IL-6) and inhibits hepatic stellate cell activation to exert anti-fibrotic effects, slowing liver fibrosis progression." (PMID 41530783, 2026). "IL‐6 is another critical cytokine involved in HSCs activation and liver fibrosis." (PMID 41487942, 2026). "Increased ROS generation, produced by oxidative stress, activates hepatic stellate cells, increases the expression of pro-inflammatory cytokines such as tumor necrosis factor-alpha (TNF-α), interleukin-6 (IL-6), and interleukin-1 (IL-1), and triggers apoptosis and liver fibrosis." (PMID 40647324, 2025). "Furthermore, antibodies-based therapies targeting the IL-6 pathway represent a potential new approach for treating liver fibrosis." (PMID 39995661, 2025). "Irradiation at high radiation doses (>30 Gy) results in the development of liver fibrosis, whereas lower doses affect hepatic function by inducing inflammatory and oxidative stresses, in which the expression of cytokines, such as IL-6 and CCL2, increases with the activation of the NFκb signaling." (PMID 40141336, 2025). "Furthermore, melatonin has been shown to attenuate thioacetamide-induced liver fibrosis in male rats by modulating IL-6, IL-4, apoptosis, and urokinase-type plasminogen activator receptor-related protein/Endo180 expression." (PMID 39995661, 2025). "As a pro-inflammatory cytokines, IL-6 participates in liver inflammatory responses and plays a critical role in liver fibrosis progression by regulating the secretion of pro-fibrotic factors, activating signaling pathway, and promoting the proliferation and differentiation of fibroblasts." (PMID 39995661, 2025). "Several studies showed that GP73 promotes chronic inflammation by upregulating the secretion of pro-inflammatory cytokines, especially Il-6, which in turn promotes the proliferation of hepatic stellate cells (HSCs), whose activation is a pivotal event for liver fibrosis development." (PMID 40075792, 2025). "Reduced glutathione may also play a role in modulating the immune response by lowering levels of inflammatory markers such as TNF-α, CRP, and IL-6, which are known to contribute to liver fibrosis and inflammation." (PMID 41281287, 2025). "Moreover, myeloid-specific IL-6Rα knockout mice (Il6raMye-/-) and IL-6-silenced mice subjected to high-fat diets exhibited reduced inflammation but increased liver fibrosis, further highlighting the complex and sometimes contradictory role of IL-6 in fibrosis." (PMID 39995661, 2025). "These levels were significantly associated with liver enzymes, steatosis, and fibrosis, indicating that elevated peripheral serum IL-6 may promote the progression of liver fibrosis to cirrhosis." (PMID 39995661, 2025). "In conclusion, our study revealed that SGLT2 inhibitors regulate sympathetic activity by increasing COMT activity associated with the correction of hypomagnesemia and may be involved in preventing liver fibrosis by inhibiting IL-6 production in KCs." (PMID 40715617, 2025). "IL-6 influences liver fibrosis progression through intricate and diverse pathways." (PMID 41296792, 2025). "Furthermore, the coculture of primary KCs and HSCs induced a more activated phenotype, which was inhibited by anti-IL-6 and siRNA-IL-627, indicating that KCs activate HSCs via the production of IL-6 and lead to liver fibrosis." (PMID 40715617, 2025). "Furthermore, the injection of SVF via the portal vein significantly reduced thioacetamide-induced liver fibrosis, with lower mRNA levels of IL-1β, IL-6, and TNF-α compared to the ASC and PBS-injected groups." (PMID 40547297, 2025).
liver fibrosis (continued). "Additionally, IL-6 induces HSCs activation and liver fibrosis via the Janus Kinase/Signal Transducer and Activator of Transcription 3 (JAK/STAT3) signaling pathway." (PMID 39995661, 2025). "In conclusion, C. sinensis could cause ferroptosis, which promoted the secretions of IL-6 and TNF-α as well as the activation of TGF-β/Smad pathway, leading to exacerbated liver fibrosis." (PMID 40455823, 2025). "Interestingly, 5-HT treatment also induced the inflammatory component of liver fibrosis as IL6 expression increased." (PMID 38228622, 2024). "Furthermore, in a rat model of CCl4-induced liver fibrosis, SM (100 mg/kg) demonstrated anti-inflammatory (IL-6) and antioxidant (GSH and MDA) protective activities." (PMID 38247522, 2024). "The present data indicated that BECs TLR3 deficiency resulted in significantly increased IL-6 and TNF secretion induced by CsEVs, which may be an important reason for more severe liver damage and liver fibrosis in TLR3-/- mice infected with C. sinensis." (PMID 37167198, 2023). "Among the cytokines that signal via the JAK-STAT pathway, IL-6 could be involved in liver fibrosis via amplifying the intercellular communication between stressed hepatocytes, HSCs and macrophages." (PMID 37860002, 2023). "Moreover, a previous study in mice treated with CCl4 showed that a combination of Il6 and mesenchymal stem cell transplantation attenuated liver fibrosis in mice." (PMID 36672739, 2023). "In addition, other liver flukes infection, such as Opisthorchis viverrini, also result in high expression of IL-6 and TNF-α, and is closely associated with the development of liver fibrosis." (PMID 36693049, 2023). "The IL-6 present in the MSC secretome induces hepatocyte proliferation, and enhances gene expression of chitinase 3-like protein 1 in HSCs, which has been associated positively with cell survival and negatively with liver fibrosis." (PMID 36831304, 2023). "Activated HSCs are identified by the overexpression of α-SMA and extreme expression of extra cellular matrix proteins (vimentin, β-catenin, and snail) through inflammatory cytokines such as TNF-α, IL-1β, and IL6, which increase the development of liver fibrosis." (PMID 37090196, 2023). "This might be regulated by TF Hlf, which facilitates liver fibrosis through activation of HSCs driven by the HLF/IL-6/STAT3 feedforward circuit." (PMID 36814339, 2023). "Especially, HSCs may respond to immunological triggers and acquire a pro-inflammatory profile by expressing more inflammatory genes, including IL-6, during liver fibrosis." (PMID 37288106, 2023). "Il6 is a key pro-inflammatory and profibrogenic cytokine that drives liver fibrosis." (PMID 36814339, 2023). "However, it is still unclear how PGC-1α influences IL-6 expression during the process of liver fibrosis induced by hepatic I/R injury." (PMID 37679346, 2023). "However, hepatocyte-derived exosomes mediated TLR3 activation in HSCs and increased IL-17 production from γδ T cells, and the IL-17 strongly stimulated the expression of a-SMA, TGF-β, IL-6, and collagen type I-α1 in HSCs and aggravated liver fibrosis." (PMID 36875101, 2023). "Interestingly, mice with ablated IL-6 had aggravated hepatocyte damage which led to more severe liver fibrosis." (PMID 36978885, 2023). "In addition, upstream mediators, such as transforming growth factor β (TGF-β), IL-6, and IL-1β (which are dependent on TNF-α), are implicated in the development of liver fibrosis." (PMID 38116551, 2023). "Furthermore, IL-6 appears to be a pivotal factor in reducing acute carbon tetrachloride (CCL4)-induced liver injury by amelioration of liver fibrosis and promotion of liver regeneration." (PMID 37587168, 2023). "TNF-α enhances survival of HSCs, immune activation and hepatocyte death, promoting liver fibrosis, whereas the high production of IL-6 in experimental- induced liver failure has shown to trigger immune suppression and disrupt liver repair, increasing mortality risk." (PMID 36544761, 2022).